NT5DC2 (5'-nucleotidase domain containing 2)
Description:
Promotes dephosphorylation of tyrosine 3-monooxygenase TH which decreases TH catalytic activity and leads to reduced synthesis of catecholamines including dopamine, noradrenaline and adrenaline. The exact mechanism of activity is unknown but may act as a phosphatase or promote the activity of phosphatases or may inhibit phosphorylation by acting as a barrier to interfere with protein kinase access.
Synonyms: FLJ12442
Tractability: PROTAC: ubiquitination databases record sites on it; its protein half-life has been measured.
Target class: Enzyme; Hydrolase
Gene: Protein-coding gene on chromosome 3 (52,524,370 to 52,535,054, reverse strand). Ensembl gene ENSG00000168268.
Subcellular location: Cytoplasm
Gene Ontology:
Molecular function: phosphatase activity
Biological process: negative regulation of dopamine biosynthetic process
Cellular component: mitochondrion; cytoplasm
Genetic constraint (gnomAD): Loss-of-function variants: 39 observed, 64.61 expected, observed/expected ratio (o/e) 0.6, 90% interval 0.47 to 0.79. The upper end of that interval is the gene's LOEUF score, 0.79, which puts it in group 3 of 6, group 1 being the genes least tolerant of losing a copy. Missense variants: 656 observed, 734.14 expected, observed/expected ratio (o/e) 0.89, 90% interval 0.84 to 0.95. Synonymous variants: 291 observed, 285.21 expected, observed/expected ratio (o/e) 1.02, 90% interval 0.93 to 1.12.
Homologues: Orthologues: macaque NT5DC2 (99% identical), dog NT5DC2 (97% identical), guinea pig NT5DC2 (97% identical), rat Nt5dc2 (96% identical), mouse Nt5dc2 (96% identical), pig NT5DC2 (96% identical), chimpanzee NT5DC2 (86% identical), rabbit NT5DC2 (78% identical), tropical clawed frog NT5DC2 (72% identical), Drosophila melanogaster Nt5c (40% identical), Drosophila melanogaster Nt5b (24% identical), Caenorhabditis elegans Y71H10B.1 (22% identical). Paralogues in human: NT5DC3 (59% identical), NT5C2 (25% identical), NT5DC4 (19% identical), NT5DC1 (18% identical).
Diseases named in the same sentence as NT5DC2 in open-access papers:
NT5DC2 is named in the same sentence as 36 diseases in open-access papers, as found by Europe PMC text mining. Sharing a sentence is not in itself a finding about the gene and the disease. The quoted sentences say what the papers report.
hepatocellular carcinoma (6 papers, 2020 to 2023). A malignant tumor that arises from hepatocytes. "Here, knockdown of NT5DC2 resulted in limited progression of colorectal cancer cell models, whereas overexpression of NT5DC2 enhanced tumor growth in leiomyosarcoma, glioma and hepatocellular carcinoma." (PMID 35326547, 2022). "The results identified a substantial upregulation of NT5DC2 in the hepatoma cell lines than normal cell line." (PMID 32382041, 2020). "The expression of NEIL3 and NT5DC2 was not obvious in hepatocellular carcinoma cells." (PMID 37745297, 2023).
leiomyosarcoma (6 papers, 2021 to 2023). An uncommon, aggressive malignant smooth muscle neoplasm, usually occurring in post-menopausal women. "The overexpression of TEAD4 was associated with poor survival, suggesting that NT5DC2 plays an important role in the development of leiomyosarcomas and may serve as a potential therapeutic target." (PMID 37576396, 2023). "This study aimed to investigate the expression profile and functional regulation of NT5DC2 and its potential interplay with TEAD4 in leiomyosarcoma (LMS)." (PMID 33993634, 2021).
colorectal cancer (5 papers, 2022 to 2023). A primary or metastatic malignant neoplasm that affects the colon or rectum. "A previous study showed that NT5DC2 deletion obviously reduced the tumor-associated macrophage (TAM) recruitments through suppressing CCL2/CCR2 and AKT/NF-κB signaling pathways in colorectal cancer." (PMID 35047040, 2022). "Currently, NT5DC2 is regarded as a biomarker for colorectal carcinoma since it regulates multiple cellular events to modulate tumor growth." (PMID 36553697, 2022).
glioblastoma (5 papers, 2020 to 2023). The most malignant astrocytic tumor (WHO grade IV). "NT5DC2 has been shown to interact with and stabilize Fyn, a Src family proto-oncogene, and plays a role in regulating glioblastoma progression." (PMID 32382041, 2020). "NT5DC2 has been shown to markedly reduce the expression of Fyn, a Src family proto-oncogene and has been implicated in glioblastoma, though not yet linked to CRC susceptibility." (PMID 32833970, 2020). "They suggested that NT5DC2 may be a promising therapeutic target for glioblastoma." (PMID 35047040, 2022).
lung cancer (5 papers, 2022 to 2024). A malignant neoplasm involving the lung. "One such molecule, 5′‐nucleotidase domain containing 2 (NT5DC2), has been identified as a critical regulator in various cancers including lung cancer." (PMID 39506204, 2024). "A study found that NT5DC2 was highly expressed in lung cancer, and overexpression of NT5DC2 promoted the proliferation, migration, and invasion of lung cancer cells." (PMID 35047040, 2022).
breast carcinoma (4 papers, 2019 to 2024). "According to our study, the expression of NT5C2, NT5DC1, and NT5DC3 was downregulated, while the expression of NT5DC2 was upregulated in breast cancer tissues." (PMID 36820551, 2023). "The low expression level of NT5DC1 (P = 7.3e–06) and high expression level of NT5DC2 (P = 1.5e–06) indicated significantly shorter OS in breast cancer patients." (PMID 36820551, 2023). "The results of the TIMER database showed that the expression of NT5C2, NT5DC1, and NT5DC3 were significantly downregulated in breast cancer tissues, while the expression of NT5DC2 were upregulated." (PMID 36820551, 2023). "In addition, NT5DC2 mediates the malignant growth of breast cancer by blocking the EGFR pathway." (PMID 39506204, 2024).
glioma (4 papers, 2021 to 2023). A benign or malignant brain and spinal cord tumor that arises from glial cells (astrocytes, oligodendrocytes, ependymal cells). "Functionally, NT5DC2 can act as a stabilizer of some oncoproteins by reducing ubiquitin‐mediated degradation, including fyn in glioma 3 and EGFR in HCC." (PMID 33993634, 2021).
liver cancer (4 papers, 2018 to 2024). An epithelial or non-epithelial malignant neoplasm that arises from the liver. "Most members of the NT5DC family are highly expressed in liver cancer, and specific studies have confirmed that elevated expression of NT5DC2 is linked to higher liver cancer stages and a poorer prognosis for patients." (PMID 37405532, 2024). "The risk model for liver cancer patients includes NQO1, NT5DC2, and S100A9 as risk genes." (PMID 37405532, 2024).
adenocarcinoma of the lung (2 papers, 2022 to 2024). "It has already been demonstrated that tumor expression of NT5DC2 is a prognostic marker of lung adenocarcinoma, with high levels of expression associated with poor survival." (PMID 39409885, 2024). "Our study identified germline variants affecting lung adenocarcinoma patient survival, possibly due to a regulatory role on gene expression, in particular of NT5DC2 and NAGK genes." (PMID 39409885, 2024). "NT5DC2 overexpression was associated with advanced lymphonodal spread and reduced survival in patients with adenocarcinoma of the lung." (PMID 35326547, 2022). "Therefore, it is more plausible that the SNPs on chromosome 3 affect lung adenocarcinoma survival through the regulation of expression of NT5DC2 gene." (PMID 39409885, 2024). "High NT5DC2 and NAGK expression in lung adenocarcinoma tissue was already shown to correlate with poor overall survival." (PMID 39409885, 2024).
sarcoma (2 papers, 2021 to 2022). A usually aggressive malignant neoplasm of the soft tissue or bone. "However, subgroup analysis in different sarcoma subtypes (with over 30 cases) only found an association between high NT5DC2 expression and unfavourable PFS in undifferentiated pleomorphic sarcoma/myxofibrosarcoma (UPS/MFS) cases." (PMID 33993634, 2021). "Therefore, NT5DC2 may be a novel biomarker and therapeutic target for sarcomas, but further studies are needed to verify its biological function and prognostic value." (PMID 35024438, 2022).
schizophrenia (2 papers, 2023 to 2025). A major psychotic disorder characterized by abnormalities in the perception or expression of reality. "NT5DC2 has been associated with schizophrenia, bipolar disorder, in relation to abnormal activity of dopamine in the brain." (PMID 41211100, 2025).
atrial fibrillation (1 paper, 2022). A disorder characterized by an electrocardiographic finding of a supraventricular arrhythmia characterized by the replacement of consistent P waves by rapid oscillations or fibrillatory waves that vary in size, shape and timing and are accompanied by an irregular ventricular response. "NT5DC2 was also previously detected as transcriptionally upregulated in studies of atrial fibrillation and pulmonary fibrosis, but little attention has been given to NT5DC2 as a potential target." (PMID 36531712, 2022).
bladder cancer (1 paper, 2026). "Functionally, we demonstrated that NT5DC2 suppresses ferroptosis in bladder cancer cells and promotes malignant tumor progression." (PMID 41974665, 2026). "In this study, we found that NT5DC2 is highly expressed in bladder cancer tissues compared with normal tissues and that its expression is correlated with the poor prognosis of bladder cancer patients." (PMID 41974665, 2026). "In addition, rescue assay results indicated that ACSL3 mediated the roles of NT5DC2 in suppressing ferroptosis of bladder cancer cells." (PMID 41974665, 2026). "Collectively, our findings suggest that NT5DC2/ACSL3 plays a critical role in bladder cancer progression and ferroptosis regulation, suggesting that NT5DC2/ACSL3 is a potential therapeutic target for bladder cancer treatment." (PMID 41974665, 2026).
diabetes (1 paper, 2017). "The obesity SNP rs2710323, together with two diabetes SNPs, rs2590838 (r2, 0.78) and rs1108842 (r2, 0.8), are located in loci that regulate genes (TMEM110, MUSTN1, ITIH4, NEK4, GNL3, PBRM1, and NT5DC2) within a 300 kb genomic region on chromosome 3." (PMID 29081791, 2017).
lymph node metastasis (1 paper, 2022). "Likewise, neither the absence of lymphonodal spread (pN0, p = 0.123) nor the presence of lymph node metastasis (pN1, p = 0.983; pN2, p = 0.746) resulted in favorable survival with respect to NT5DC2 protein expression." (PMID 35326547, 2022).
melanoma (1 paper, 2025). A malignant, usually aggressive tumor composed of atypical, neoplastic melanocytes. "Analysis of the TCGA-SKCM and GTEx datasets revealed elevated expression of NF2, SUZ39H1, CDC25A, GLRX5, and CISD3 in melanoma tissues, in contrast with the reduced expression of VDR, PPARD, CAMKK2, NT5DC2, and CHP1A." (PMID 40860143, 2025).
tumor (21 papers, 2018 to 2026). "Analyzing the GSE40144 dataset showed that NT5DC2 expression was associated with tumor node metastasis (TNM) stages although the difference didn’t reach a significant level." (PMID 32382041, 2020). "Furthermore, NT5DC2 expression was associated with larger tumor size and microvascular invasion, and was independently associated with RFS." (PMID 37576396, 2023). "We used three datasets (BRCA_GSE110686, BRCA_GSE114727_10X, and BRCA_GSE114727_inDrop) of the TISCH web tool to interpret NT5C2 and NT5DC2 expression in tumor microenvironment-related immune cells." (PMID 36820551, 2023). "High expression of NT5C2, NT5DC2, and NT5DC3 was closely associated with higher tumor stage and poor overall survival (OS)." (PMID 35047040, 2022). "Our findings showed that NT5C2, NT5DC2, and NT5DC3 expression was associated with higher tumor pathologic stage and poor OS." (PMID 35047040, 2022). "Our study reports for the first time that NT5DC2 overexpression promotes HCC cell proliferation and clone formation by regulating the cell cycle and promoting tumor growth in subcutaneous xenografts, while NT5DC2 knockdown inhibits these processes." (PMID 32382041, 2020). "In vivo studies have shown that overexpression of NT5DC2 promotes tumor growth, and downregulation of NT5DC2 inhibits tumor growth." (PMID 32382041, 2020). "Tumoral tissues showed significantly higher NT5DC2 expression compared with that of peritumoral tissues." (PMID 32382041, 2020). "However, the exact mechanisms by which NT5DC2 regulates tumor development of LUSC, particularly with regard to macrophage polarization, are not fully understood." (PMID 39506204, 2024). "Several recent studies revealed that NT5DC2 upregulation might enhance the malignant phenotypes of some tumours, such as facilitated cell‐cycle progression, proliferation, EMT, angiogenesis, metastasis and cancer stem cell properties." (PMID 33993634, 2021). "The present study demonstrated for the first time that NT5DC2 promotes tumor cell proliferation in HCC and may serve as a potential molecular target for treating HCC." (PMID 32382041, 2020). "Importantly, upregulation of NT5DC2 in tumor tissue indicates a poor prognosis." (PMID 32382041, 2020). "Research has demonstrated that NT5DC2 is upregulated in TNBC, promoting tumor progression and neuropathic pain through interactions with the epidermal growth factor receptor (EGFR) to activate downstream signaling." (PMID 40109861, 2025). "We observed that the expression of NT5C2 (P=0.0055), NT5DC2 (P=0.027), and NT5DC3 (P=0.035) was closely correlated with tumor stage, suggesting that the expression of NT5C2, NT5DC2, and NT5DC3 increased significantly with the progression of HCC." (PMID 35047040, 2022). "In combination with other findings in the current study, we proposed a positive feedback loop between NT5DC2 and TEAD4 in LMS tumour cells." (PMID 33993634, 2021). "The expression of four proteins (MCM3, RRM2, NT5DC2, and RNASEH2A) was significantly upregulated in HCC tissues compared to that in non-tumor tissues." (PMID 32213663, 2020). "After describing the individual roles of the ferroptosis-related genes (G6PD, KIF20A, EZH2, NT5DC2, SLC7A11), it is essential to investigate how these genes might interact with each other to influence the tumor microenvironment (TME) in a synergistic manner." (PMID 40465746, 2025). "Thus, NT5DC2 silencing inhibits LUSC cell proliferation, tube formation, glycolysis, tumor formation, and M2 macrophage polarization and induced cell apoptosis." (PMID 39506204, 2024).
tumor (continued). "Compared with normal tissues, the expression levels of BEX1 in tumor tissues were significantly different, while the GCLM, G6PC, NEIL3 and NT5DC2 protein bands were unclear, which may be related to their low expression levels." (PMID 37745297, 2023). "Many studies showed that NT5C2, NT5DC2, and NT5DC3 played an important role in tumor development." (PMID 35047040, 2022). "Furthermore, overexpression of NT5DC2 was reported to promote the proliferation of HCC cells in vitro and to facilitate tumor growth in vivo." (PMID 36290827, 2022). "The correlation between NT5DC2 expression and EGFR expression in 79 HCC tumor tissues was examined." (PMID 32382041, 2020). "To further explore the specific cellular expression patterns of these genes in HCC, we conducted scRNA-seq data to identify the distribution of G6PC, GCLM NEIL3 and NT5DC2 in different cell subclusters in HCC tissues including HCC tumor cells and non-tumor cells." (PMID 37745297, 2023).
cancer (11 papers, 2020 to 2026). A tumor composed of atypical neoplastic, often pleomorphic cells that invade other tissues. "NT5DC2, a gene associated with ferroptosis, has been identified as a key facilitator of cellular proliferation and metastasis in several cancers." (PMID 41974665, 2026). "NT5DC2 is a 5′-nucleotidase that can catalyze the hydrolysis of nucleotides and has been associated with psychiatric disorders and cancer." (PMID 36531712, 2022). "This too might allow for further investigation of NT5DC2 in combination with cancer associated fibroblasts." (PMID 35326547, 2022). "Its upregulation was found to enhance the growth and metastasis of cancer cells by acting as a sponge for miR-1322 and activating NT5DC2." (PMID 40302808, 2025). "Subsequently, the analysis of clinical LUSC tissues and lung tissues showed that NT5DC2 expression at mRNA and protein levels was upregulated in cancer tissues." (PMID 39506204, 2024). "Studies have shown that NT5DC2 is upregulated in several types of cancers, such as hepatocellular carcinoma and NSCLC." (PMID 39506204, 2024). "The TIMER database is employed to visualize the differential expression levels of NT5DC2 across the Pan‐Cancer dataset derived from The Cancer Genome Atlas (TCGA)." (PMID 39506204, 2024). "The expression levels of NT5DC2/3 proteins were significantly correlated with the cancer stages of PAAD." (PMID 37576396, 2023). "Previous data have revealed that NT5DC2 can bind to Fyn and thus promote cancer progression." (PMID 39506204, 2024). "We detected the expression of the other six genes (MCM3, SPATS2, RRM2, NT5DC2, LRRC1, and RNASEH2A) in 30 pairs of HCC and para-carcinoma tissue by immunohistochemical staining assays." (PMID 32213663, 2020). "While it does not directly examine the role of NT5DC2 in cancer, it provides basic information about the gene and its expression patterns." (PMID 40302808, 2025).
infection (1 paper, 2023). The state of being infected such as from the introduction of a foreign agent such as serum, vaccine, antigenic substance or organism. "The correlation between high NT5DC2 expression and metastases in pathogen infection-induced GC has remained unknown." (PMID 37800836, 2023).
NT5DC2 also shares sentences with these, for which no sentence is quoted: adenocarcinoma (2 papers); acute leukemia (1); Alzheimer disease (1); astrocytoma (1); autism (1); bipolar disorder (1); diffuse large B-cell lymphoma (1); gastric cancer (1); hepatoblastoma (1); myxofibrosarcoma (1); non-small cell lung carcinoma (1); Obesity (1); psychiatric disorder (1); pulmonary fibrosis (1); squamous cell tumor (1); thymoma (1); undifferentiated pleomorphic sarcoma (1).